BCAT1 (branched chain amino acid transaminase 1)
Diseases named in the same sentence as BCAT1 in open-access papers (continued):
Sharing a sentence is not in itself a finding about the gene and the disease.
tumor (continued). "Also, our data indicates that BCAT1 high expression is strongly linked to the disease-free survival, tumor size, pathologic stage, T classification and differentiation grade." (PMID 31226958, 2019). "In addition, the clinical data indicated that the expression of BCAT1 was significantly associated with tumor size, pathologic stage, T classification and differentiation grade of ESCC patients." (PMID 31226958, 2019). "BCAT1 has been reported to promote tumour proliferation, invasion, migration, cell cycle progression and apoptosis through multiple pathways." (PMID 40687583, 2025). "The interaction between G6PD, DNMT1, and BCAT1 in tumors presents an opportunity to develop new treatment methods that target tumor metabolism." (PMID 41462671, 2025). "Isoform-Specific Contributions: How does BCAT1 versus BCAT2 overexpression differentially affect tumor metabolism and growth in distinct cancer contexts?" (PMID 40507232, 2025). "Collectively, these BCAT1 inhibitors demonstrate that targeting a single metabolic enzyme can have broad anti-tumor effects and even enhance other treatments." (PMID 41502503, 2025). "Potential therapeutic targets for cystine transporters and BCAT1 to inhibit tumor growth and progression by inhibiting these targets." (PMID 40786181, 2025). "For example, an EGFR inhibitor plus a BCAT1 inhibitor tackled two separate resistance mechanisms in lung cancer models and achieved deeper tumor regressions than either alone." (PMID 41502503, 2025). "A key consideration for clinical trials will be selecting patients whose tumors are BCAT1-driven (e.g., by measuring BCAT1 expression or activity in the tumor) so that those most likely to benefit receive the treatment." (PMID 41502503, 2025). "Enzymes such as branched-chain amino acid transaminase 1 (BCAT1) are upregulated in NSCLC and have been associated with tumor aggressiveness and poor clinical outcomes." (PMID 40469185, 2025). "BCAT1 promotes tumor growth by supporting amino acid metabolism, redox balance, and oncogenic signaling." (PMID 41584609, 2025). "The silencing of BCAT1 in an orthotopic TNBC xenograft model resulted in a massive tumor volume reduction in vivo." (PMID 38971778, 2024). "Several physiological and pathological processes, encompassing tumour growth and metastasis, cell cycle, apoptosis, pyroptosis, and angiogenesis, are under the regulatory influence of BCAT1-mediated BCAA catabolism." (PMID 38309289, 2024). "CRIP1 was specific to the tumor region, whereas BCAT1 and FXYD3 were confined to the stromal region." (PMID 39135097, 2024). "Hypomethylation of BCAT1 was also highly correlated with factors such as tumor progression and advanced age in various clinical features." (PMID 39324007, 2024). "By performing analysis through the UALCAN database, we obtained the expression of BCAT1 in different molecular subtypes, different genders, different grades, different N-stages and different tumor stages of KIRC." (PMID 39324007, 2024). "The size and weight of the tumour xenografts derived from HuR KO1 cells overexpressing BCAT1 were significantly increased compared with those of tumour xenografts derived from HuR KO1 cells without BCAT1 at three weeks." (PMID 38369471, 2024). "Given the essential role of DNA repair pathways in tumor initiation and progression, we focused our investigation on the functional consequence of BCAT1-KU complex interaction." (PMID 39769333, 2024). "In summary, our study is the first to identify HuR as a potential tumour promoter that accelerates CRPC progression by post-transcriptionally upregulating BCAT1 and activating ERK5 signalling in CRPC cells." (PMID 38369471, 2024). "And by using the UALCAN tool, we found that the methylation level of BCAT1 was decreased in KIRC tumor tissues." (PMID 39324007, 2024). "Genetic depletion or pharmacological inhibition of BCAT1 impaired the growth of resistant cells and partially re-sensitized tumor cells to EGFR TKIs." (PMID 39143065, 2024).
tumor (continued). "Collectively, these results underscore that CHIP-mediated BCAT1 degradation effectively inhibits tumor growth in vivo." (PMID 39075053, 2024). "Jared et, al reported elevated BCAT1 expression in non-small cell lung cancer, and loss of BCAT1 impairs NSCLC tumor formation." (PMID 39075053, 2024). "In our analysis of TCGA data using UALCAN, we found that BCAT1 was highly expressed in the tumor tissues of KIRC patients and that patients with high BCAT1 expression had higher tumor grades and more lymph node metastases." (PMID 39324007, 2024). "The inhibition of BCAT1 expression results in the reduction of glutamate and therefore inhibit tumor growth and invasion." (PMID 38218942, 2024). "We identified BCAT1 expression levels in KIRC tumor tissues and paraneoplastic tissues in the TCGA database and found that BCAT1 expression was significantly elevated in tumor tissues." (PMID 39324007, 2024). "Taken together, these results showed that BMS-202 positively regulated the expression of BCAT1 by activating Akt to inhibit tumor progression in GBM." (PMID 38438374, 2024). "We found that knockdown of BCAT1 significantly impaired the ability of 67R cells to form tumors, leading to a noticeable decrease in both tumor formation rate and tumor weight." (PMID 39143065, 2024). "They found that BCAT1 activated cancer progression, and suppressing this pathway reversed BCAT1-induced tumor growth." (PMID 39409942, 2024). "The results showed that the BCAT1 expression was significantly higher in macrophages and tumor cells than that in other cell types, consistent with the former analysis." (PMID 38309289, 2024). "Previous studies confirmed that BCAT1 is involved in many pathways to regulate downstream factors during tumour progression." (PMID 38369471, 2024). "Tumor cells use BCAAs as fuel, increasing the expression of BCAT1 and catabolizing them to provide glutamine." (PMID 37637065, 2023). "BCAT1 knockdown significantly reduced the tumor size compared to the size of the tumors in the control group." (PMID 37298317, 2023). "Tumor cells showed infiltration into the peripheral brain tissues in the BCAT1 wild-type groups, whereas tumors had a sharp and clear border in the BCAT1 knockdown group." (PMID 37298317, 2023). "In contrast, high levels of BCAT1 have been shown to promote the tumor growth and a decreased sensitivity to CDDP." (PMID 36824411, 2023). "The high expression of BCAT1 was positively correlated with tumor diameter, lymphatic metastasis, and a poor prognosis." (PMID 38028625, 2023). "The hypermethylation of the BCAT1 promoter inhibits the BCAT1 gene, and the decrease in the expression of BCAT1 reduces the supply of glutamate, increases the dependence on glutaminase, and reduces tumor proliferation and invasion." (PMID 38028625, 2023). "Immunohistochemistry showed that A11 tumor BCAT1 expression was co-localized with the expression of the monocarboxylate transporters MCT1 and MCT4, which are also HIF transcriptional targets, and with CAIX." (PMID 37885806, 2023). "It has been discovered that BCAT1 is overexpressed at the protein level in tumor cells and tissues isolated from patients with metastatic lung cancer." (PMID 37637065, 2023). "Multiple studies have reported that BCAA transaminase 1 (BCAT1), the rate-limiting enzyme of BCAA catabolism, is associated with tumor aggressiveness and drug resistance in several tumor types." (PMID 35011702, 2022). "When used as a biomarker for the discrimination between tumor/control samples, BCAT1 showed notable accuracy, with an area under the ROC curve (AUC) of 0.85." (PMID 36123616, 2022). "During treatment with bevacizumab, it was found that BCAT1 appears to induce drug resistance by promoting tumor proliferation and glutamate excretion." (PMID 36119495, 2022). "Consistent with this previous work, we demonstrated successful knockdown of BCAT1 by RNAi effectively repressed SCLC cell proliferation through inducing tumour cell apoptosis." (PMID 35318805, 2022).
tumor (continued). "Branched chain amino acid transaminase 1 (BCAT1), which is overexpressed in a variety of tumors and promotes tumor progression, is upregulated by TMPO-AS1 through the targeting miR-98-5p, which in turn promotes CRC cell stemness." (PMID 35155247, 2022). "Taken together, BCAT1 is likely to be a tumor biomarker related to tumor immune cell infiltration, and it demonstrates the potential of immune treatment for multiple cancers." (PMID 34984849, 2022). "This indicates that BCAT1 are important in the tumor progression of upper tract urothelial cancer (UTUC) and UBUC." (PMID 36119495, 2022). "In liver cancer, BCAT1 expression is significantly elevated in HCC tissues compared to non-tumor tissues." (PMID 35011702, 2022). "Further analysis in TCGA demonstrated that CCT2 was upregulated in tumor tissues compared with normal tissues and positively correlated with BCAT1 expression." (PMID 34164393, 2021). "Individually, the knockdown of BCAT1 or cisplatin therapy in the HepG2 cells reduced the tumor volume." (PMID 33568627, 2021). "In the present study, we verified that BCAT1 was overexpressed in GC patients with poor prognosis through analyzing data from The Cancer Genome Atlas (TCGA) and clinical tumor samples." (PMID 34164393, 2021). "Here, we verified the higher expression of BCAT1 in GC tumor tissues compared with normal tissues in both TCGA data and clinical samples, similar to the results of previous studies." (PMID 34164393, 2021). "The knockdown or pharmacological inhibition of BCAT1/2 results in decreased proliferation and tumor growth of BCAT1/2-dependent cancer cells." (PMID 34203535, 2021). "The addition of LY294002 reversed the tumor growth induced by BCAT1 overexpression, further verifying this mechanism." (PMID 34164393, 2021). "The expression of the BCAA metabolic enzyme, such as the cytosolic branched-chain aminotransferase 1 (BCAT1) was reported to correlate in EC with more aggressive cancer growth and progression—it is related to tumor grade, FIGO stage and lymph node metastasis." (PMID 34518615, 2021). "Given that patients with a higher percentage of mesenchymal CTCs had significantly shorter time of tumor recurrence, therefore, the effect of BCAT1 was also examined in the EMT process." (PMID 32610709, 2020). "qRT-PCR showed that the expression of BCAT1 in tumor tissues was markedly increased compared with that in adjacent normal tissues in patients with GC (P < 0.001)." (PMID 32855634, 2020). "Functional exploration suggested that knockdown of BCAT1 inhibited the proliferation of OS cells, indicating it as a tumor promoter in OS." (PMID 32269179, 2020). "Although BCAT1 is required for tumor growth and progression in a wide range of malignancies, BCAT1 inhibition impairs all three BCAAs metabolism." (PMID 31409769, 2019). "The role of BCAT1 in cancer progression has become an intriguing but challenging topic to understand, with several different functions in tumor growth having been proposed [12▪,18▪▪]." (PMID 29211698, 2018). "Most tumour tissues displayed elevated methylation of both BCAT1 and IKZF1 (n = 78, 85.7%), while ctDNA methylated in both genes was only detected in 30 patients (33.0%)." (PMID 29796114, 2018). "The only variables having any effect on methylation levels in cancers were age older than 65 years and tumour location for BCAT1." (PMID 29796114, 2018). "Knockdown of BCAT1 repressed the cell proliferation and invasiveness in vitro and inhibited the tumor growth in the xenograft model." (PMID 29541009, 2018). "A second study on the role of BCAT1 in macrophages found that glioblastoma cells secrete BCKAs via the monocarboxylate carrier 1 (MCT1) and that these BCKAs are taken up by tumor-associated macrophages." (PMID 29502308, 2018). "Deregulation of IKZF1 and BCAT1 is involved in tumour growth and invasiveness in several cancers, including CRC." (PMID 29796114, 2018).
tumor (continued). "The past few years of in-depth research on BCAA metabolism in cancer has provided strong evidence for the essential role of BCAAs in tumor progression and has clearly established BCAT1 as an important prognostic cancer marker." (PMID 29211698, 2018). "Among the volumetrics parameters, only the tumor volume based on FLAIR images had a significant correlation with the BCAT1 expression level (r = −0.2579, P = 0.0324)." (PMID 29255149, 2017). "We found significant positive correlations between the BCAT1 expression level and MR imaging features, including the mean nCBV and 95% nCBV from the tumor extents based on FLAIR images and 95% nCBV value from the enhancing area based on CE T1WI." (PMID 29255149, 2017). "Multiple regression analysis revealed that the only tumor volume (P = 0.0294) and mean ADC value (P = 0.0407) based on FLAIR images were significantly correlated with BCAT1 expression level independently with IDH1 mutation status." (PMID 29255149, 2017). "Tumor volume ratio (log10%) in IDH1 WT was significantly increased after bevacizumab treatment than BCAT1 sh#1 rats (2.3210 [IQR, 2.2505–2.6005] vs 2.1370 [1.9173–2.2232]; p = 0.0181)." (PMID 27626306, 2016). "Here, given the known role of BCAT1 in tumor cell proliferation and invasiveness, we investigate the bevacizumab resistance increased by BCAT1 expression in IDH1 WT GBM rat models using DSC perfusion MRI." (PMID 27626306, 2016). "Nevertheless, nCBV of IDH1 WT rats increased after bevacizumab treatment, which seems to be correlated to excreted glutamate by BCAT1 activity fueled to the tumor cell for proliferation, suggesting that it induces resistance." (PMID 27626306, 2016). "The disappearance of circulating methylated BCAT1 and IKZF1 DNA after tumour resection in 10 of 12 cancer cases shows that detection of methylated BCAT1 and IKZF1 DNA in the blood reflects the presence of CRC rather than a risk of developing CRC." (PMID 26445409, 2015). "BCAT1 was first identified from a c-Myc-induced tumor and has been proven to be directly regulated by c-Myc through its binding to the specific DNA sequence, CACGTG." (PMID 23758864, 2013). "Furthermore, targeted inhibition of BCAA metabolism and BCAT1 has been shown to impede tumor progression." (PMID 40274762, 2025). "Mutations in the codon responsible for encoding BCAT1 have been identified in clinical GC samples, and these mutations result in higher enzymatic activity of BCAT1, which promotes BCAA catabolism and accelerates cell growth motility and tumor development." (PMID 40018041, 2025). "BCAT1 inhibition suppresses MCD DLBCL tumor growth in vitro and in vivo." (PMID 40924473, 2025). "Several studies demonstrated that methylation patterns of SEPT9, SDC2, and BCAT1 in plasma (circulating tumor DNA) could distinguish CRC from benign polyps with high diagnostic accuracy (AUC = 0.914)." (PMID 41514609, 2025). "BCAT1, as a key enzyme in branched-chain amino acid metabolism, promotes tumor cell proliferation." (PMID 40313460, 2025). "Moving forward, one could envision using a BCAT1 inhibitor to “soften up” a tumor before hitting it with chemotherapy or a targeted agent—the metabolic stress might make cancer cells less able to cope with the subsequent assault." (PMID 41502503, 2025). "However, BCAT1 inhibition doesn’t uniformly suppress tumor growth, and its ability to promote progression and metastasis isn’t universally acknowledged." (PMID 38309289, 2024). "We have performed Western Blot on tumor tissue and paracancerous tissue from 21 pairs of clinical specimens and immunohistochemical staining on 20 of them, all of which showed significant overexpression of BCAT1 in KIRC." (PMID 39324007, 2024). "Gene Set Enrichment Analysis (GSEA) highlights the potential impact of BCAT1 on pathways related to tumor invasion and proliferation, including cytokine-cytokine receptor interaction, ECM receptor interaction, TGF-β signaling pathway, and JAK/STAT signaling pathway." (PMID 38309289, 2024).
tumor (continued). "Moreover, the carcinogenic effect of BCAT1 on CRPC was further confirmed by tumour xenografts derived from PC3 cells overexpressing BCAT1." (PMID 38369471, 2024). "In HCC patients, the level of BCAT1 was found to be higher in circulating tumor cells." (PMID 38993559, 2024). "Besides clinical database analysis, we collected clinical tumor samples and detected BCAT1 expression using immunohistochemical staining." (PMID 39143065, 2024). "However, mice xenografted with U87-CHIP/BCAT1K360R cells displayed a resumption of tumor volume and weight, confirming that CHIP inhibited tumor growth through BCAT1 degradation." (PMID 39075053, 2024). "In addition, immunohistochemical staining confirmed that the administration of KH-3 reduced Ki67 and BCAT1 expression in tumour xenografts derived from PC3 cells." (PMID 38369471, 2024). "In addition, the volume and weight of the tumour xenografts derived from BCAT1-overexpressing PC3 cells were markedly increased compared to those of tumour xenografts derived from sgControl PC3 cells." (PMID 38369471, 2024). "Moreover, immunostaining revealed that the expression of BCAT1 in tumour xenografts derived from HuR KO cells was decreased compared with that in tumour xenografts derived from sgControl cells." (PMID 38369471, 2024). "Additionally, ongoing efforts are focused on developing more selective BCAT1 inhibitors with enhanced efficacy and evaluating their performance in established tumor models." (PMID 39143065, 2024). "Moreover, 67R- and AZDR-resistant xenograft tumors also showed elevated expression of BCAT1 compared with the parental tumor tissues." (PMID 39143065, 2024). "Additionally, single-gene RNA sequencing analysis demonstrated significant enrichment of BCAT1 in macrophages and tumor cells." (PMID 38309289, 2024). "Inhibiting BCAT1 can subsequently repress tumor growth, proliferation, and invasion." (PMID 38305803, 2024). "Additionally, Myc upregulates BCAT1, a crucial enzyme in BCAAs catabolism, and increases biosynthesis and promotes tumor development." (PMID 38218942, 2024). "BCAT1/2 upregulation has been shown to be a marker of tumor aggressiveness across many tumor types." (PMID 37732074, 2023). "In addition, up-regulation of BCAT1 expression increases glycolysis, providing favorable conditions for tumor proliferation." (PMID 36119495, 2022). "Besides, the inhibition of BCAT1 expression suppresses glutathione production, which disrupts tumor redox balance." (PMID 36119495, 2022). "Studies have shown that BCAT1 can resist cisplatin-induced cell death, and inhibiting the expression of BCAT1 can partially block the autophagy response of cancer cells, thereby regulating the sensitivity of cisplatin and reducing tumor drug resistance." (PMID 36119495, 2022). "BCAT1 could increase cell drug resistance, and inhibit the expression of BCAT1 can inhibit tumor development." (PMID 36119495, 2022). "Tumor patients with distinct clinical features may have different prognoses, so we explored the correlation between BCAT1 expression and clinical features." (PMID 34984849, 2022). "Inhibition of DNMT1 and, or BCAT1 activity may inhibit tumor development by blocking this proliferative pathway." (PMID 36119495, 2022). "In addition, BCKAs, the catabolite of BCAT1-mediated BCAA catabolism, can be excreted by tumor cells, and then be absorbed by tumor-associated macrophages (TAMs)." (PMID 35736497, 2022). "IHC staining for BCAT1 expression was negative or weakly positive in paracarcinoma tissues but positive in tumor tissues and even strongly positive in tumors with metastasis, implying that BCAT1 expression may be related to GC progression." (PMID 34164393, 2021). "However, tumors from the cells with BCAT1 knockdown exhibited a significantly enhanced response to cisplatin, leading to a significant reduction in tumor size and weight." (PMID 33568627, 2021).